ZEB2 (zinc finger E-box binding homeobox 2)
Diseases named in the same sentence as ZEB2 in open-access papers (continued):
Sharing a sentence is not in itself a finding about the gene and the disease.
prostate carcinoma (continued). "For example, in induced pluripotent stem cells (iPSC) and prostate cancer cells, mesenchymal genes, such as ZEB1, ZEB2, CDH2, TWIST and SNAI1/2, are enriched with EZH2 binding, but not epithelial genes such as CDH1 or SNAI3." (PMID 37175580, 2023). "This analysis revealed a striking positive correlation between the expression of PKCα (PRKCA gene) and mesenchymal markers vimentin, ZEB1, ZEB2, and AXL in prostate cancer cell lines." (PMID 36818489, 2022). "For example, DNMT1 induces histone demethylation of H3K9me3 and H3K27me3 on the promoters of Zeb2 and KLF4 in prostate cancer cells." (PMID 33616161, 2021). "This is in accordance with different studies, which uncovered that miR-203 directly targets its upstream regulator ZEB2, suppressing EMT in lung adenocarcinoma, nasopharyngeal carcinoma, prostate cancer, and clear cell renal cell carcinoma." (PMID 32708601, 2020). "Additionally, TSA also led to prostate cancer aggressiveness via induction of epithelial-to-mesenchymal transition phenotype which associated with increased expression of transcription factors ZEB1, ZEB2 and Slug, and mesenchymal markers such as vimentin, N-cadherin and fibronectin." (PMID 28785170, 2017). "We provided first evidence that miR-203 represses EMT by directly targeting Zeb2 and other EMT regulators, including Bmi1, that in turn regulate invasion and metastasis of prostate cancer." (PMID 27588490, 2016). "TMPRSS2/ERG fusion gene indirectly up-regulates ZEB2, a facilitator of the epithelial to mesenchymal transition (EMT), by binding to IL1R2 to increase prostate cancer tumorigenesis." (PMID 24359571, 2013). "Furthermore, the KM plotter and GEPIA results demonstrated that when prostate cancer progresses, there are changes in the expression of CDH1, CDH2, VIM, SNAI1, ZEB1, and ZEB2." (PMID 40693059, 2025). "Moreover, miR-200c-3p was found to remarkably inhibit the formation of migration and invasion in prostate cancer cells via suppression of E-cadherin-induced Epithelial-mesenchymal transition (EMT), achieved by targeting ZEB2." (PMID 34524611, 2021). "CRABP2, HPD, ZEB2 and CDK5R1 are the common DEGs both in breast and prostate cancer." (PMID 33407865, 2021). "In prostate cancer, ZEB2 was shown to be involved in a double negative feedback loop with miR-145, and indeed ZEB2 and miR-145 levels are negatively correlated in prostate cancers." (PMID 32192092, 2020). "This miRNA normally targets ZEB2, and this double negative feedback loop regulates epithelial-mesenchymal transition in prostate cancer cells." (PMID 28430163, 2017). "In addition, miR-205 was shown to directly target Zeb2, N-chimaerin, ErbB3, E2F1 and E2F5 in prostate cancer cells." (PMID 27588490, 2016). "SSX2 knockdown, in the 22Rv1 prostate cancer line, demonstrated a large fold change in many different EMT associated genes (TWIST1, ZEB2, MMP2, VIM, CDH1, CDH2) however these genes did not respond in an anticipated or canonical way." (PMID 27276714, 2016). "Remarkably, ZEB2 was also found to directly repress the transcription of miR-145, establishing a double-negative feedback loop between ZEB2 and miR-145 with strong implications for prostate cancer metastasis." (PMID 26784241, 2016). "During EMT of prostate cancer cells, the expression of transcription factors such as Snail, Slug, Twist, E47, ZEB1, and ZEB2 is increased, which leads to increased expression of N-cadherin and vimentin and concomitantly decreased expression of E-cadherin and cytokeratins." (PMID 23785446, 2013). "Interestingly, a well-known gene fusion in prostate cancer that is produced by deletion of a 3-mega base region between ERG and TMPRSS2 (also reviewed in [Parker 2014 Journal of Pathology]) has also been found to upregulate ZEB1 and ZEB2 expression." (PMID 24598126, 2014).
bladder cancer (46 papers, 2012 to 2025). "The clinical association of TGFβ1, ZEB2NAT transcripts and ZEB2 protein were further confirmed in 17 human bladder cancer samples." (PMID 26152796, 2015). "For instance, ZEB2 overexpression also caused resistance to DNA damage-induced apoptosis and correlated with a poor outcome in bladder cancer patients." (PMID 23658743, 2013). "Our results indicate that the TGFβ-Smad2/3 signaling pathway-induced EMT process is involved in GCB resistance in bladder cancer by transactivating Slug and ZEB2 and downregulating hCNT1 and hENT1." (PMID 33922395, 2021). "Our findings indicated that TGF-β signaling induced EMT in GCB-resistant bladder cancer cells by activating Smad2/3, thereby upregulating Slug and ZEB2 and ultimately reducing hENT1 and hCNT1, the major influx transporters of GCB." (PMID 33922395, 2021). "lncRNA TUG1 expression by miR142-mediated zinc finger E-box binding homeobox 2 (ZEB2), through inactivating the Wnt/β-catenin pathway, promoted the proliferation of bladder cancer cells and induced apoptosis." (PMID 34039257, 2021). "lncRNA TUG1 affected proliferation by miR-299-3p/VEGF pathway, ZEB2/miR-142/wnt/β-catenin pathway, microRNA496/wnt/β-catenin pathway in renal cell carcinoma, bladder cancer, prostate cancer, respectively." (PMID 34039257, 2021). "In bladder cancer cells, the expression of miR-377 undergoes down-regulation by circZFR to promote cancer metastasis through ZEB2 stimulation." (PMID 32664703, 2020). "The key regulators of the EMT process are E-cadherin, N-cadherin, vimentin, Snail, Slug, Twist, and Zeb-2, and most of these have been correlated with bladder cancer progression via either genetic or epigenetic regulation." (PMID 32517366, 2020). "Then, we further detected ZEB2 protein expression in bladder cancer tissues by immunohistochemistry (IHC)." (PMID 31746333, 2019). "This lncRNA has been found to be upregulated in both urinary bladder cancer and hepatocellular carcinoma, and in bladder cancer cells is partly responsible for activation of ZEB2 during EMT induction by Transforming growth factor beta (TGF-β)." (PMID 29701689, 2018). "In bladder cancer, TUG1 decreased the expression of miR-145 and caused upregulation of ZEB2, miR-145 target, promoting EMT, and increasing the metastatic proneness of bladder cancer cells." (PMID 29147648, 2017). "In clinicopathological interpretation, increased ZEB1 and ZEB2 expression have been reported in human bladder carcinoma tissue, and ZEB2 represented as an independent factor of poor prognosis in the radiotherapy treated bladder cancer patients." (PMID 27058893, 2016). "Consistently, TGFβ1 mRNA expression is positively correlated with ZEB2NAT transcript and ZEB2 protein levels in human bladder cancer specimens." (PMID 26152796, 2015). "Our data confirm that mesenchymal markers (Zeb-1, Zeb-2, MMPs, and vimentin) are expressed almost exclusively by muscle-invasive tumors, the subset of bladder cancer with worse outcome." (PMID 22253920, 2012). "On one hand, it has been reported that elevated ZEB2 expression correlated positively with adverse patient survival in breast, ovarian, kidney, oral and bladder cancers." (PMID 22393452, 2012). "lncRNA-UCA1 induces EMT in bladder cancer cells by up-regulating the expression levels of zinc-finger E-box-binding homology boxes 1 and 2 (ZEB1 and ZEB2), and it regulates bladder cancer cell EMT through the tumor suppressor hsa-miR-145 and its target gene FSCN1." (PMID 40689207, 2025). "ZEB2 expression has been reported across various tumors, including bladder cancer." (PMID 40689207, 2025). "lncRNA TUG1 has been found to enhance radioresistance in bladder cancer via miR-145/ZEB2 axis." (PMID 35600868, 2022). "Additionally, both miR‐374b‐5p and miR‐454‐3p exert inhibitory effects by regulating ZEB2 in bladder cancer." (PMID 34890108, 2022).
bladder cancer (continued). "Moreover, NORAD and ZFAS1 have been reported to promote cell invasion and migration in cervical cancer and bladder cancer, respectively, by up-regulating ZEB2." (PMID 36514044, 2022). "Mechanistically, we observed that circZFR could directly bind to miR-377 as sponge to promote ZEB2 expression in bladder cancer cells." (PMID 31746333, 2019). "In addition, rescue assays demonstrated that restoration of ZEB2 significantly impaired the suppressive effects of circZFR silencing on bladder cancer cells growth, migration and invasion." (PMID 31746333, 2019). "Similarly, the transforming growth factor-β (TGFβ)-induced antisense RNA Zeb2/Sip1 in bladder carcinoma cells binds to the 5’UTR-splicing site of the ZEB2 transcript and prevents its degradation." (PMID 30441811, 2018). "In addition, ZEB2 protects bladder cancer and squamous carcinoma cells from cisplatin- and ultraviolet-induced apoptosis, and this pro-survival effect of ZEB2 is independent on ZEB2-mediated EMT induction and cell cycle arrest." (PMID 29416649, 2018). "For example, miR-138-5p could inhibit the translation of ZEB2 mRNA and suppress the ZEB2-mediated metastatic potential of bladder cancer." (PMID 27978829, 2016). "In human bladder cancer cell lines, we observed a direct correlation between E-cadherin and p63 expression, and an inverse correlation between these markers and Zeb-1, Zeb-2, and vimentin, indicating they cluster into unique “epithelial” and “mesenchymal” subsets." (PMID 22253920, 2012). "Interestingly, ZEB2 also protects bladder cancer cells from radiation-induced apoptosis." (PMID 40689207, 2025). "Taken together, our results illuminated that circZFR could be a prognostic biomarker in bladder cancer and exerted oncogenic roles through regulating miR-377/ZEB2 axis in bladder cancer, which indicated that circZFR could be a potential therapeutic target for bladder cancer patients treatment." (PMID 31746333, 2019). "Besides chromatin modification, MALAT-1 also functions as transcription regulator through activating Wnt signaling pathway, which results in increasing of ZEB1, ZEB2, Snail2 and decreasing of E-cadherin in bladder cancer, or suppressing PI3K-AKT pathway and inhibiting EMT in breast cancer." (PMID 27992370, 2017). "In urinary bladder cancer, TGFβ from CAFs induces EMT by regulating ZEB2 through both transcriptional activation and upregulation of ZEB2NAT, a long noncoding RNA that promotes ZEB2 translation." (PMID 40173050, 2025). "In bladder cancer cells, lncRNA TUG1 increases ZEB2 expression by inhibiting miR‐142 and inhibits the Wnt/β‐catenin pathway to promote cell proliferation and inhibit apoptosis." (PMID 35421276, 2022). "We further investigated these genes using the Oncomine database, and the results also indicated lower expression of PDE5A, RECK, ZEB2, and CYBRD1 in bladder cancer tissue than in normal bladder mucosa." (PMID 33987019, 2021). "T24-Exos or J82-Exos also induced the expression of the EMT-transcription factors Slug, Snail, Twist and Zeb2, which ultimately suppressed E-cadherin expression but promoted N-cadherin, vimentin, MMP2 and MMP9 expression in bladder cancer cells." (PMID 32517366, 2020). "In bladder cancer, it was found that indoleamine-2,3-dioxygenase-1 (IDO1) induces ZEB2 overexpression, which in turns increases the viability and proliferation of cancer cells." (PMID 32664703, 2020). "The experiments in vitro suggested that knockdown of ZFAS1 repressed bladder cancer cell proliferation via up-regulating KLF2 and NKD2 expression, and inhibited cell migration and invasion via down-regulating ZEB1 and ZEB2 expression." (PMID 29678899, 2018). "Ectopic overexpression of ZEB2NAT, which was founded in bladder cancer recently, prevents splicing of the ZEB2 5’-UTR, increases the levels of Zeb2 protein, and consequently downregulates E-cadherin mRNA and protein." (PMID 27992370, 2017).
bladder cancer (continued). "In bladder cancer miR-200b and miR-200c have been reported to reduce expression of ZEB1, ZEB2, and ErbB receptor inhibitor-1 and therefore inhibit EMT and restore epidermal growth factor receptor dependency." (PMID 27058893, 2016). "Additionally, in bladder cancer, lncRNAs like TUG1 and SNHG1 have been shown to modulate autophagy through interactions with signaling pathways such as miR-145/ZEB2 and PP2A catalytic subunit, respectively." (PMID 39512820, 2024). "In bladder cancer, miR-138 binds to the 3′TUR sequence of ZEB2 (zinc finger E-box binding homeobox 2), regulates the expression and phosphorylation of vimentin and e-cadherin, reverses the EMT process, and enables cancer cells to obtain epithelial characteristics." (PMID 31885571, 2019). "Furthermore, ΔNp63α‐mediated expression of miR‐205 contributed to the regulation EMT in bladder cancer cells, and that miR‐205 prevented EMT through suppression of ZEB1 and ZEB2." (PMID 29150940, 2018). "Thus, knockdown of ZFAS1 repressed bladder cancer cell proliferation via up-regulating KLF2 and NKD2 expression, and inhibited cell migration and invasion via down-regulating ZEB1 and ZEB2 expression." (PMID 29678899, 2018). "MiR-429, as other members of miR-200 family, act as a tumor suppressor roles during bladder cancer progression by reducing ZEB1, ZEB2 and restoring E-cadherin which results in downregulation of β-catenin and therefore inhibits cell migratory and invasive ability." (PMID 27058893, 2016). "Additionally, along the miR-145/ZEB2 pathway, the lncRNA TUG1, which is significantly expressed at an elevated level in bladder cancer samples and cells, promotes epithelial-mesenchymal transition (EMT) and reduces the susceptibility of cancer cells to ionizing radiation." (PMID 39512820, 2024). "Further analysis of gene expression from the GEO dataset indicated lower expression of PDE5A, RECK, ZEB2, and CYBRD1 in bladder cancer tissue than in normal bladder mucosa, which indicated that PDE5A, RECK, ZEB2, and CYBRD1 may act as tumor suppressors in UTUC." (PMID 33987019, 2021).
glioma (42 papers, 2012 to 2025). A benign or malignant brain and spinal cord tumor that arises from glial cells (astrocytes, oligodendrocytes, ependymal cells). "Further, to explore its associated molecular mechanisms in glioma cells, we examined the effect of targeted silencing of ZEB2 gene on cell proliferation, EMT, and cell apoptosis using siRNA in vitro." (PMID 22761708, 2012). "ZEB2 has previously been confirmed to be associated with the malignant phenotype of glioma, and the expression level of ZEB1 was significantly increased in glioma tissues compared to normal brain tissues, being positively correlated with WHO glioma classification." (PMID 40679044, 2025). "Overexpression of miR-192-5p could repress ZEB2 expression in glioma cells, while inhibiting miR-192-5p caused upregulation of ZEB2 expression." (PMID 36193069, 2022). "In this review, we aimed to summarise the current knowledge with a regard to functional experiments considering the impact of miRNA and lncRNA as well as other epigenetic modifications, with a main focus on ZEB1 and ZEB2 in gliomas." (PMID 37239035, 2023). "The miRNAs that are known to affect ZEB1/ZEB2 act as tumour suppressors and are significantly downregulated in various glioma samples and cell lines." (PMID 37239035, 2023). "Tumourigenesis and histogenesis of gliomas are modulated by ING5, a tumour suppressor; its overexpression decreases the level of Snail, Slug, Twist1, ZEB1 and ZEB2 in glioma cells and inhibited tumour growth in a xenograft mouse model." (PMID 37239035, 2023). "The expression of SNAIL, SLUG, TWIST, ZEB1, and ZEB2 enables glioma cells to shift toward a mesenchymal phenotype." (PMID 38092725, 2023). "Previously, HOTAIRM1 is also revealed to accelerate the malignant progression of glioma by regulating ZEB2, a competing endogenous RNA targeting molecule that interacts with miR-873-5p." (PMID 38012763, 2023). "Previously, HOTAIRM1 has been shown to accelerate malignancy of glioma through regulating ZEB2, a competing endogenous RNA targeting molecule that interacts with miR-873-5p." (PMID 38012763, 2023). "ZEB2 is an established regulator of EMT and has been linked to increased invasiveness and migration, poor prognosis for glioma patients, and is upregulated in glioblastoma and in DIPG as demonstrated in this study." (PMID 35590427, 2022). "Its downregulation in gliomas is controlled by HIF1α via the activation of ZEB2, resulting in cancer cell invasion and anti-angiogenic resistance." (PMID 35205289, 2022). "In previous studies, ZEB2 has been recognized as a key biomarker in glioma, which promotes proliferation, migration, and invasion by inducing EMT process." (PMID 36193069, 2022). "It was demonstrated that knockdown of circ_0000189 or ZEB2 weakened the lung metastasis of glioma cells, but circ_0000189 overexpression promoted the lung metastasis." (PMID 36193069, 2022). "What is more, it was proved that the circ_0000189/miR-192-5p/ZEB2 axis was involved in promoting glioma progression." (PMID 36193069, 2022). "Recurrences are significantly more common in GBM patients with high ZEB2 levels, and glioma cells become more invasive when activated nuclear factor-B induces ZEB1 expression." (PMID 35163279, 2022). "Our results proposed a novel competitive endogenous RNA (ceRNA) network composed of circi_0000189, miR-192-5p, and ZEB2, which was involved in glioma progression." (PMID 36193069, 2022). "Quantitative real-time polymerase chain reaction (qRT-PCR) was utilized to detect the expression levels of circ_0000189, miR-192-5p, and ZEB2 mRNA in glioma tissues and cells." (PMID 36193069, 2022). "qRT-PCR showed that miR-192-5p expression in the tissues of 50 glioma patients and the expression of ZEB2 mRNA were negatively correlated." (PMID 36193069, 2022).